CSF1R (colony stimulating factor 1 receptor)
Diseases named in the same sentence as CSF1R in open-access papers (continued):
Sharing a sentence is not in itself a finding about the gene and the disease.
tumor (continued). "Emerging therapeutic approaches, such as CSF-1R inhibitors and immune-modulating agents, aim to reprogram TAMs to support anti-tumor immunity, facilitating the transition from a cold-to-hot tumor transition in BC." (PMID 40281554, 2025). "In these additional models, the increase in macrophage secretion of VEGF-A in response to tumor cell CSF-1 was again suppressed through addition of CSF-1R inhibitors or blocking antibodies." (PMID 40646332, 2025). "In some cancers, high CSF-1 expression is associated with a poor prognosis, and inhibition of the CSF-1/CSF-1R pathway increases anti-tumor activity." (PMID 39488822, 2025). "A preclinical study reported that the simultaneous blockade of colony-stimulating factor 1 receptor (CSF1R) and anti-PD-1 antibodies resulted in reprogramming M2 TAMs into M1 and promoting tumor regression." (PMID 40075727, 2025). "Given the more robust depletion of subcortical microglia with CSF1R inhibition, we next tested the role of reactive microglia in the subcortical oligodendroglial dysfunction observed following tumor-clearing CAR T cell therapy." (PMID 38798554, 2024). "Surufatinib (Sulanda) 18 is an oral multi-kinase inhibitor with dual function against angiogenesis (VEGFR-1, -2, -3 and FGFR) and tumor immune evasion (CSF-1R: colony stimulating factor-1 receptor)." (PMID 38362086, 2024). "The functional consequences of CSF-1R expression in tumor cells make it an interesting target for anti-cancer therapy." (PMID 38254773, 2024). "We observed a robust reduction in tumor growth in the anti-CSF1R and IL-33 + anti-CSF1R groups compared with the control group." (PMID 38238529, 2024). "In glioblastoma mouse models, inhibition of CSF-1R resulted in significant reduction of tumor size and long-term survival." (PMID 39195299, 2024). "Clinical studies have demonstrated that RG7155 significantly reduced the number of CSF-1R-positive TAMs in tumor biopsies during treatment." (PMID 39575419, 2024). "Several studies have shown that the prolonged inhibition of CSF-1R can result in acquired resistance and consequently tumor relapse via activation of the PI3K pathway." (PMID 39409110, 2024). "The link between SOX9, expressed in tumor cells, and the CSF-1R, expressed by TAMs and particularly by the M2-like subset, is mediated by LIF/LIFR signaling." (PMID 39457693, 2024). "Although it was previously thought that anti-CSF-1R therapeutic strategies only targeted M2-TAMs, the evidence demonstrating CSF-1R expression in cancer cells and its contribution to tumor growth makes this receptor an interesting target for therapy." (PMID 38254773, 2024). "These recruited TAMs, in turn, release more M-CSF, binding to CSF-1R on the surface of tumor cells, forming a positive feedback loop that facilitates continuous growth and survival of tumor cells." (PMID 38646440, 2024). "Targeting the CSF1/CSF1R axis in combination with chemotherapy decreased tumor burden and increased overall survival of mice." (PMID 39682696, 2024). "Pexidartinib is a polygenic tyrosine kinase inhibitor that targets CSF-1R to significantly mitigate macrophage tumor infiltration." (PMID 38341519, 2024). "CSF1-R inhibitors have been shown to effectively eliminate TAMs and halt tumor growth, angiogenesis, and metastasis." (PMID 39682696, 2024). "Inhibitors targeting the CCL2/CCR2 or CSF-1/CSF-1R signaling axis have shown promise in reducing macrophage accumulation at tumor sites." (PMID 39146202, 2024). "Due to the failure of monotherapy using CSF1R inhibitors, researchers are currently exploring combinatorial therapies as a promising approach to target the tumor from different angles." (PMID 38665919, 2024). "Accordingly, the depletion of macrophages with the monoclonal antibody against CSF1R favoured intratumoural infiltration of cytotoxic T cells specifically in the context of SEMA3Ahigh tumours." (PMID 38670629, 2024).
tumor (continued). "A thorough understanding of the significance of CSF-1R expression in tumor cells will greatly help in developing therapeutic drugs that specifically target the neoplastic component, for single use or in combination with other anti-cancer therapies." (PMID 38254773, 2024). "Targeted proteomics identified IL-6 and M-CSF as dominant drivers, and we show that IL-6R and CSF1R inhibition prevents tumor-induced CD14+ cDC2s." (PMID 38242119, 2024). "This potent anti-tumor activity of anti-CSF-1R drugs has been mostly attributed to its action on TAMs and other myeloid-derived cells." (PMID 38254773, 2024). "Several phase I and II studies have tested CSF-1R targeting drugs in the form of monoclonal antibodies or tyrosine kinase inhibitors to overcome the tumor resistance in macrophage-rich solid tumors." (PMID 38638445, 2024). "Beyond changes in tumor size, pilot studies have described other specific MRI findings following CSF1R inhibitors." (PMID 38254890, 2024). "Tumor-associated macrophages (TAMs) demonstrated significant upregulation of CD163, CD68, and CSF1R." (PMID 39484208, 2024). "On day 7, tumor-bearing mice was treated with a small molecule inhibitor of CSF-1R (Ki20227) for 1 week." (PMID 38554213, 2024). "The recruitment of macrophages and myeloid cells into the tumor microenvironment can be prevented through the inhibition of CCL2/C–C chemokine receptor type 2 or CSF1/CSF1-R." (PMID 39682696, 2024). "They used nano micelles loaded with PI3K inhibitor BEZ 235 and CSF1R-siRNA to reduce M2-type macrophage levels in tumor tissues through the synergistic effect of both." (PMID 39916962, 2024). "offer an explanation for this outcome as acquired resistance to CSF-1R inhibition was correlated with increased insulin-like growth factor signaling between TAMs and tumor cells." (PMID 39272914, 2024). "For example, colony-stimulating factor 1 (CSF1) or CSF1 receptor (CSF1R) blockade has been shown to repolarize M2 to M1 macrophages and increase tumor sensitivity to other immunotherapies." (PMID 38612926, 2024). "Significantly, DNA sequencing unveiled missense mutations in ABL, CCND3, CSF1R, KDR, and FGFR4, potentially contributing to tumor progression and angiogenesis in PF." (PMID 38732067, 2024). "An in vitro assay demonstrated the involvement of the CSF-1/CSF-1R axis in tumor migration via anoikis resistance and the induction of pro-angiogenic factor expression, such as VEGFA, in GC tissues." (PMID 38254773, 2024). "Used in combination with immunomodulators, such as CSF1R inhibitors and anti-PD-1 antibodies, the macrophage exhaustion state can be further suppressed and the anti-tumor immune response enhanced." (PMID 39416792, 2024). "Blockade of CSF-1R signaling can reshape the tumor microenvironment and enhance immune responses, making CSF-1R an attractive target combined with FGFR for cancer therapy." (PMID 38172256, 2024). "According to this study, CSF-1/CSF-1R expression correlated with an advanced stage of disease in young patients and tumor metastasis." (PMID 38254773, 2024). "Inhibiting CSF-1R signaling can reduce anti-inflammatory TAMs and promote a pro-inflammatory phenotype, improving anti-tumor immune responses." (PMID 38288307, 2024). "The upregulation of SLC7A11 induces the infiltration of tumor-associated macrophages (TAMs) and MDSCs by activating the colony-stimulating factor 1 (CSF1)/colony-stimulating factor 1 receptor (CSF1R) axis." (PMID 38397901, 2024). "Through the paracrine loop involving CSF-1R and epidermal growth factor, this mechanism enhances the interaction between tumor cells and macrophages, further promoting the migration and infiltration of tumor cells." (PMID 38646440, 2024). "The selected compound BPR1R024 exhibited potent in vitro CSF-1R inhibition and specifically targeted pro-tumorigenic M2-like TAMs while sparing anti-tumor M1-like TAMs." (PMID 39457693, 2024).
tumor (continued). "Pharmacological inhibition of colony-stimulating factor 1 (CSF-1)/CSF-1R axis inhibited TAMs and impaired tumor progression." (PMID 38542388, 2024). "The combined use of Pexidartinib and Sotuletinib (BLZ945), another CSF-1R inhibitor, reduced the proliferation of tumor cells, their spheroid formation ability, as well induced apoptosis in correlation with CSF-1R levels in TGCT." (PMID 38254773, 2024). "CSF − 1R is a transmembrane tyrosine kinase receptor, and the binding of CSF-1 to CSF-1R on the cell surface exerts pro-tumor effects." (PMID 38303927, 2024). "First, we tested the effect of CSF1R inhibition alone or in combination with gemcitabine on the survival of mice bearing tumours from either Sema3a high or low cells." (PMID 38670629, 2024). "For example, blocking CSF1R by PLX3397 effectively suppresses tumor growth and metastasis and sensitizes CRLM to 5-FU or anti-PD-1/-CTLA-4." (PMID 39125923, 2024). "Given the significant role of CSF-1R in tumor immune modulation, our focus was primarily on the roles of FGFR and CSF-1R in the context of sulfatinib." (PMID 38172256, 2024). "By combining paclitaxel with a CSF1R signaling antagonist, studies have shown an effective reduction in macrophage recruitment to tumor sites, thereby enhancing the drug’s effectiveness and reducing tumor progression and metastasis in preclinical models." (PMID 39717759, 2024). "In this context, other groups confirmed that CSF-1R blockade in TAMs can induce the development of an anti-tumor and immunostimulatory milieu within the TME." (PMID 39457693, 2024). "Our finding that simultaneous inhibition of IL-6R and CSF1R drastically reduces tumor-induced cDC2 to CD14+ DC conversion creates several therapeutic possibilities." (PMID 38242119, 2024). "It has been found that proliferation, recruitment, differentiation from a tumoricidal to a tumor-promoting phenotype, and survival of macrophages depend on CSF-1/CSF-1R axis." (PMID 39003350, 2024). "The results showed that the proportion of CSF-1R-positive M2-type macrophages in the peritoneal cells of tumor-bearing mice was increased after paclitaxel treatment." (PMID 38303927, 2024). "The CSF1R inhibitor Pexidartinib prevented TAM from being stimulated to differentiate into M2-type macrophages by CSF1 secreted by tumor cells." (PMID 39916962, 2024). "Studies performed in a mouse tumor model demonstrated that blockade of CSF-1R using a specific inhibitor (BLZ945) reduced the aggregation of MDSCs and shrunk tumor size." (PMID 38717677, 2024). "The role of the PLX-3397, its target, colony-stimulating factor 1 receptor (CSF1R), and impact on macrophages has been mainly investigated in the tumor environment." (PMID 38546923, 2024). "Accumulating evidence has highlighted the pivotal role of CSF1R in various tumor contexts, underscoring its influence on the proliferation, differentiation, and most importantly, the immunosuppressive function of MDSCs." (PMID 38992688, 2024). "Upon CTLA-4 blockade, tumor-infiltrating MDSCs exhibit increased expression of colony-stimulating factor-1 receptor (CSF-1R), which in turn is correlated with increased MDSC infiltration in tumors." (PMID 38520006, 2024). "anti-Csf1r effectively hinders the accumulation of Trem2+ Macrophages in HCC tumor tissues and synergistically enhances the therapeutic efficacy of anti-PD-1." (PMID 38948071, 2024). "For example, TAMs’ ability to support tumor invasion has been thoroughly investigated, and it relies on the CSF-1R-mediated activation of PI3K and Src family kinase (SFK) pathways." (PMID 39457693, 2024). "For patients with recurrent or metastatic HNSCC, 800 mg/day of the CSF1R-targeted drug Pazopanib oral suspension in combination with standard weekly cetuximab had observed encouraging preliminary anti-tumor activity." (PMID 38279056, 2024). "Nonetheless, although high CSF-1R levels were detected in specific tumor models, its expression in MDSCs remained inconsistent across different tumor types." (PMID 39457693, 2024).
tumor (continued). "Research has also found that the combination of CSF1R inhibitors with anti-PD-L1 therapy is more effective in preventing tumor growth than single treatments." (PMID 38646440, 2024). "Methods include the use of TLR agonists, IFN-γ and CSF1R inhibitors, etc., which promote the production of pro-inflammatory cytokines and anti-tumor factors by altering the polarization state of macrophages to enhance the overall anti-tumor immune response." (PMID 39416792, 2024). "Combination therapies using BLZ945 and other CSF-1R inhibitors are showing promise in boosting anti-tumor immunity." (PMID 39796695, 2024). "By contrast, neutralization of IFNγ fully rescued tumor growth, while depletion of TAMs using a colony-stimulating factor 1 receptor (CSF1R) antibody partly rescued tumor growth." (PMID 37996514, 2024). "Recent findings support the blockade of CSF1R in vivo in cancers leading to an immune permissive tumor microenvironment." (PMID 39622842, 2024). "BLZ945 (CSF-1R inhibitor) can also effectively control tumor growth when combined with PD-1/PD-L1 blocking antibody." (PMID 38970071, 2024). "Suppressive tumor microenvironment reversion like targeting MDSCs using phosphodiesterase inhibitors, CSF-1R inhibitors, etc." (PMID 39076974, 2024). "CSF1R inhibitors such as Pexidartinib (PLX3397) have shown promising anti-tumor effects in preclinical and clinical studies." (PMID 39416792, 2024). "Anti-CSF1R therapy resulted in reduced tumor volume, F4/80 infiltration, and proliferation of macrophages as well as blood vessel formation." (PMID 39172519, 2024). "CSF1R is implicated in the recruitment of macrophages to the TME, and their polarization to an anti-tumor M2 phenotype." (PMID 39660126, 2024). "Emactuzumab (RG7155), a novel humanized antibody targeting CSF-1R, has been observed to decrease the number of TAMs expressing CSF-1R in tumor lesions." (PMID 39146202, 2024). "Targeting the CSF1-CSF1 receptor (CSF1R) axis has a comprehensive effect on the tumor immune microenvironment." (PMID 40458305, 2024). "Combined treatment with LNCs@CSF1R siRNA and anti-PD-1 significantly slowed tumor growth and reduced MDSC abundance within CRC tumors." (PMID 38992688, 2024). "A paracrine EGFR/CSF-1R interaction exists between TAMs and tumor cells in which CSF-1 stimulates macrophages to release EGF, leading to tumor cell proliferation and migration." (PMID 39003350, 2024). "Remarkably, integrating PARP inhibitors with CSF1R-blocking antibodies significantly enhanced anti-tumor immunity, thereby prolonging survival in these mice." (PMID 38185636, 2024). "CSF-1R inhibitors have been developed to inhibit tumor progression by suppressing macrophage differentiation toward the M2 phenotype and macrophage-related angiogenesis." (PMID 39003350, 2024). "This review summarizes the current data available on the expression and activity of CSF-1R in different tumor types." (PMID 38254773, 2024). "Other studies investigated CSF-1R targeting as a means to ablate MDSCs by reducing their pro-tumor activity." (PMID 39457693, 2024). "The interaction between M-CSF and its receptor CSF-1R holds a central position in regulating the tumor microenvironment, particularly in the context of signaling crosstalk between TAMs and tumor cells." (PMID 38646440, 2024). "The authors initially employed the CSF1R inhibitor PLX5622 or the genetic tool Clec4fcreCsf1rf/f/Spi1f/f to deplete KCs in tumor‐bearing mice, and the results demonstrated a significant increase in liver metastatic tumor cells in KC‐deficient mice." (PMID 39220104, 2024). "Blockade of CSF-1R altered the macrophage phenotype and reprogrammed the immunosuppressive cell population in the tumor microenvironment." (PMID 38303927, 2024). "In the TC-1 tumor model, in vivo administration of antibody against colony-stimulating factor 1 receptor (CSF1R), which regulates macrophage growth and differentiation delayed tumor growth." (PMID 39702544, 2024).
tumor (continued). "When the CXCR2 blockade was combined with either CSF-1R inhibition or checkpoint blockade, tumor responses were improved." (PMID 39273502, 2024). "Colony Stimulating Factor 1 Receptor (CSF1R) is a key component found in TAM that influences tumor monocyte recruitment and shapes its function within the TME." (PMID 38974237, 2024). "Structure-guided blockade of the CSF1-receptor (CSF1R) kinase has been employed, leading to prolonged regression in tumor volume in most patients." (PMID 38254890, 2024). "They demonstrated that inhibiting CSF-1R activity with a novel bioisostere of pexidartinib not only suppressed tumor growth in vivo but also inhibited CSC sphere formation in culture." (PMID 39457693, 2024). "In certain other solid tumors, such as prostate cancer and osteosarcoma, macrophage-targeting strategies on CSF1R have also shown efficacy in suppressing tumor development." (PMID 39169402, 2024). "For example, administration of Docetaxel, in combination with BLZ945, a CSF-1R inhibitor, significantly prevented tumor growth, decreased TAMs’ density, increased CD8 + T cell infiltration, and inhibited lung metastasis in mouse models of EOC." (PMID 39003350, 2024). "The histopathological and molecular features of the tumor, including mutations in ABL1, CCND1, CSF1R, FGFR4, KDR, and MALAT1-GLI1 fusion, are elucidated and discussed in the context of diagnostic, prognostic, and therapeutic considerations." (PMID 38732067, 2024). "Blocking the CSF-1/CSF-1R signaling axis can convert TAMs from a tumor-promoting phenotype to a tumor-killing phenotype." (PMID 39403370, 2024). "Several CSF-1R inhibitors, including small molecules and neutralizing antibodies, have been developed over the last years, and many drugs targeting the CSF-1R are currently in clinical development or approved for tumor treatment for many tumor types." (PMID 38254773, 2024). "The colony-stimulating factor 1 receptor (CSF-1R) plays a pivotal role in orchestrating cellular interactions within the tumor microenvironment (TME)." (PMID 39457693, 2024). "For HRP patients, targeting indolent CAFs, targeting M2 macrophages via CSF‐1/CSF‐1R inhibitors, targeting bystander T cells via tumor vaccines, and targeting epithelial cells via HDAC inhibitors." (PMID 39136172, 2024). "RT combined with the CSF1R inhibitor exerted tumor-suppressive effect partly by acting on macrophages." (PMID 39165639, 2024). "SEMA3A high tumours responded poorly to both gemcitabine and CSF1R inhibition as monotherapy, and only the combination significantly extended the survival of the mice." (PMID 38670629, 2024). "TNBC secretes cytokine CSF-1, which binds to the CSF-1 receptor (CSF-1R) on TAMs and stromal cells like mesenchymal stem cells (MSCs) that drive their recruitment to the primary tumor and increase metastasis to the lymph nodes and lungs." (PMID 39409110, 2024). "These two effects were mechanistically linked, as these effects on CD8+ T cells were blunted when macrophages were depleted from tumours by treatment with anti-CSF-1R." (PMID 38418879, 2024). "A multitude of preclinical investigations have underscored that the inhibition of CSF1R leads to a decreased density of TAMs, resulting in the inhibition of tumor growth and heightened sensitivity to chemotherapy." (PMID 38650924, 2024). "Overexpression of CSF-1 and CSF-1R on M2 macrophages represents a significant factor contributing to adverse tumor prognosis." (PMID 38646440, 2024). "For example, a study showed that the early and sustained depletion of TAMs using an anti-mouse CSF-1R antagonist antibody robustly inhibited tumor growth via T cell immune-mediated mechanisms in BALB/c mice models bearing mouse renal adenocarcinoma." (PMID 39457693, 2024). "It is a novel CSF1R-selective inhibitor with potent anti-tumor activity in vitro and in vivo, capable of removing M2-like TAMs from tumors." (PMID 39065562, 2024).